GBA2 (glucosylceramidase beta 2)
Diseases named in the same sentence as GBA2 in open-access papers (continued):
Sharing a sentence is not in itself a finding about the gene and the disease.
amyotrophic lateral sclerosis (2 papers, 2020). Amyotrophic lateral sclerosis (ALS) is a neurodegenerative disease characterized by progressive muscular paralysis reflecting degeneration of motor neurons in the primary motor cortex, corticospinal tracts, brainstem and spinal cord. "A case of overexpression of GBA2 has been reported in the spinal cord of a superoxide dismutase mutant mouse model for amyotrophic lateral sclerosis (ALS), a fatal disease resulting in loss of motor neuron function." (PMID 33261081, 2020). "In addition, a recent investigation has shown that ambroxol facilitates and protects motor units, improves axonal plasticity, and extends overall survival via inhibiting nonlysosomal (GBA2) glucocerebrosidase activity in the spinal cord with amyotrophic lateral sclerosis (ALS) in the SOD1G86R mice." (PMID 32309438, 2020).
Autosomal recessive spastic paraplegia type 46 (2 papers, 2020 to 2022). "Variants in the GBA2 gene have been associated with SA, autosomal recessive spastic paraplegia type 46 (SPG46) and Marinesco-Sjögren syndrome (MSS)." (PMID 35277195, 2022).
Cognitive impairment (2 papers, 2024 to 2025). Abnormal cognition is characterized by deficits in thinking, reasoning, or remembering. "For example, mental retardation in SPG15/ZFYVE26 and SPG46/GBA2, cognitive impairment and epilepsy in SPG35/FA2H and SPG84/PI4KA." (PMID 39932116, 2025).
colon cancer (2 papers, 2022). "For example, down-regulation of GBA1 and GBA2 was found in colon cancer, whereas overexpression of GBA1 was observed in breast cancer." (PMID 35330102, 2022).
glaucoma (2 papers, 2019 to 2024). Increased pressure in the eyeball due to obstruction of the outflow of aqueous humor. "We found similar levels of GBA and UGCG and lower GBA2 immunoreactivity in glaucoma compared to controls." (PMID 31022733, 2019). "We found significant differences in glucosylsphingosine lipids, consistent with decreased GBA and GBA2 and increased ASAH1 and ASAH2 immunoreactivity in glaucoma, suggesting the potential impairment of sphingolipid enzymatic pathways in lysosomal and nonlysosomal cellular compartments." (PMID 31022733, 2019).
hereditary spastic paraplegia 46 (2 papers, 2019 to 2020). "Growing evidence suggests a tight connection between GBA2 activity and motor functions, as full loss of function of GBA2 is a cause of hereditary spastic paraplegia type 46 (SPG46)." (PMID 31447678, 2019).
Intellectual disability (2 papers, 2025). "Case 2 had a novel de novo heterozygous in silico pathogenic variant GBA2 NM_020944.3 c.1688-2A > C. His clinical symptoms included axial hypotonia, intellectual disability, spasticity, and hyperreflexia in the lower limbs." (PMID 41153514, 2025).
lysosomal storage disease (2 papers, 2015 to 2024). A metabolic disorder caused by mutations in proteins critical for lysosomal function, including lysosomal enzymes, lysosomal integral membrane proteins, and proteins involved in the post-translational modification and trafficking of lysosomal proteins. "Loss of function mutations in GBA1 leads to the accumulation of glucocerebroside, causing related lysosomal storage disease, while non lysosomal GBA2 can lead to the accumulation of GlcCer in various tissues outside the lysosome, such as the testes and liver." (PMID 39698091, 2024). "Examples include autosomal-recessive cerebellar spasticity, which was recently been found to be caused by mutations in the GBA2 gene and many lysosomal storage disorders." (PMID 25908616, 2015).
male infertility (2 papers, 2015 to 2020). The inability of the male to effect fertilization of an ovum after a specified period of unprotected intercourse. "In mice, administration of the GBA2 inhibitor miglustat and disruption of the Gba2 gene elevate the glucosylceramide level in testis, spleen, and brain and impair spermatogenesis, resulting in male infertility." (PMID 32492073, 2020).
cerebellar disorder (1 paper, 2015). Diseases that affect the structure or function of the cerebellum. "Recent reports have indicated a clear association between GBA2 mutations and the development of cerebellar disorders and motor neuron neurodegeneration." (PMID 26418157, 2015).
cystic fibrosis (1 paper, 2023). Autosomal recessive disorder caused by pathogenic variants in the CFTR gene (cystic fibrosis transmembrane conductance regulator), which encodes a chloride and bicarbonate channel expressed in epithelial cells, and follow the diagnosis criteria. "GSL can play a regulatory role in the airway of lung inflammatory fibrotic diseases, such as Cystic fibrosis, and inhibition of GBA2 can control the role of Cystic fibrosis inflammatory response." (PMID 37168863, 2023).
keloid (1 paper, 2023). An irregularly shaped, elevated mark on the skin caused by deposits of excessive amounts of collagen during wound healing. "We explored the potential role of GSL metabolism pathway in keloid, classfied keloids based on GSLMRGs expression patterns, provided a set of gene markers including GLTP, GALC, ARSA, HEXB, SUMF2, and GBA2, and constructed a diagnostic model for keloid." (PMID 37168863, 2023). "In this study, the differential GSLMRGs of keloid and the top ten genes with the highest importance from machine learning algorithms Random Forest and SVM-RFE were intersected, and six candidate GSLMRGs were identified: ARSA, GBA2, SUMF2, GLTP, GALC, and HEXB." (PMID 37168863, 2023).
liver cancer (1 paper, 2023). An epithelial or non-epithelial malignant neoplasm that arises from the liver. "Meanwhile, the higher expression levels of GBA2 seem to be associated with better survival probability in liver cancer patients with microvascular invasion or stage III/IV, which is consistent with our additive interaction results." (PMID 38260847, 2023). "Similarly, GBA2 mRNA in HCC was lower than that in normal liver tissues, and the higher expression levels of GBA2 seemed to be associated with better survival probability in liver cancer patients with microvascular invasion or stage III/IV." (PMID 38260847, 2023).
mast syndrome (1 paper, 2015). "Such conditions include HSP with thin corpus callosum (SPG11/15 mutations), SPG35/FA2H-associated HSP, Troyer syndrome (SPG20) and Mast syndrome (SPG21), SPG26/B4GALNT1, SPG30/KIF1A, SPG39/PNPLA6 and SPG46/GBA2." (PMID 25480570, 2015).
neuropathy (1 paper, 2017). A disorder affecting the nervous system that manifests with pain, tingling, numbness, and/or muscle weakness. "Whether similar mechanisms occur in neurons, underlying the development of neuropathy in the absence of GBA2, is not known." (PMID 29234271, 2017). "The role of sphingosine in the development of neuropathy in GBA2 knockout mice has not been investigated yet." (PMID 29234271, 2017).
Niemann-Pick disease (1 paper, 2019). A group of inherited, severe metabolic disorders in which sphingomyelin accumulates in lysosomes in cells. "Conversely, pharmacological inhibition of GBA2 activity has been shown to improve the motor phenotype (e.g., motor coordination) of an animal model of Niemann’s Pick disease." (PMID 31447678, 2019).
Niemann–Pick type C diseases (1 paper, 2024). "Inhibition of GBA2 is a side effect of N-butyl-deoxynojirimycin (miglustat), a registered treatment for GBA1-deficient type 1 GD and Niemann–Pick disease type C (NPC) patients." (PMID 39246358, 2024).
non-small cell lung carcinoma (1 paper, 2020). A group of at least three distinct histological types of lung cancer, including non-small cell squamous cell carcinoma, adenocarcinoma, and large cell carcinoma. "Although nonpathological variants of GBA2 have rarely been described, recently it was reported that GBA2 variants are predictive for response to chemotherapy in non-small-cell lung cancer." (PMID 33261081, 2020).
progressive ataxia (1 paper, 2019). "The GBA2 gene was identified related to SPG46 in 2013 and GBA2 mutations were also related with progressive ataxia." (PMID 31289639, 2019).
respiratory tract infectious disorder (1 paper, 2021). Invasion of the host RESPIRATORY SYSTEM by microorganisms, usually leading to pathological processes or diseases. "Ambroxol, a beta-glucocerebrosidase 2 (GBA2) inhibitor originally indicated as a generic expectorant and mucolytic drug to treat respiratory tract infectious disorders, has been recently found to be a potential drug candidate for ALS treatment." (PMID 34992533, 2021).
scoliosis (1 paper, 2024). A congenital or acquired spinal deformity characterized by lateral curvature of the spine. "Probands were enrolled in five different centres and underwent neurological examination, clinical cognitive assessment, column imaging for scoliosis assessment, ophthalmologic examination, brain imaging, GBA2 activity in peripheral blood cells and genetic testing." (PMID 38334933, 2024).
Tangier disease (1 paper, 2020). "Why reducing GSL levels with miglustat or inhibiting GBA2, an additional target of miglustat, in NPC is therapeutically beneficial is still poorly understood in NPC, and is equally enigmatic in Tangier disease." (PMID 31707734, 2020).
viral infection (1 paper, 2025). "The enzyme CMAH is critical for the sialome, particularly the neurotrophin GM1, a critical hub for viral infection and for NMJ stability, but which is lost from NMJs at the beginning of denervation, probably due a 10-fold increase in spinal cord glucosylceramidases (non-lysosomal GBA2)." (PMID 41227379, 2025).
tumor (6 papers, 2017 to 2024). "Furthermore, eQTL analysis revealed that the GBA2 rs1570247 A allele was associated with increased mRNA expression levels, and GBA2 may play a role in regulating immune cell infiltration in the tumor microenvironment." (PMID 38260847, 2023). "However, since GBA2 can cleave glucosylceramide to produce ceramides, ceramides have been shown to act as tumor suppressors in a variety of tumors." (PMID 38260847, 2023). "Meanwhile, based on the role of GBA2 in inflammatory response, we analyzed the relationship between GBA2 and immune cell infiltration in the tumor microenvironment, and found that GBA2 was positively correlated with B cells, but negatively correlated with M2 macrophages." (PMID 38260847, 2023). "Both the GCS and the GBA1 expression levels were significantly up-regulated in CCA tumor tissues, whereas the GBA2 and GBA3 were down-regulated compared with matched paired non-tumor CCA tissues." (PMID 35330102, 2022). "According to the GEO database, GCS was overexpressed in CCA tumor tissues and showed higher expression than the two glucosylceramide-degrading enzymes, GBA1 and GBA2." (PMID 35330102, 2022). "The RT-qPCR analysis showed that PLCE1, ST8SIA1, ST3GAL5, and GBA2 were aberrantly regulated between the tumor and nontumor cell lines, while the results of PTGS1 and AMT showed no significance." (PMID 38454278, 2024). "Similar to previous reports, our study depicted that GBA2 upregulation repressed the malignant behaviors of CRC cells, indicating that GBA2 might work as a tumor suppressor in CRC." (PMID 38454278, 2024). "In other reports, non-lysosomal β-glucosidase (GBA2) hydrolyzed GlcCer to release ceramide and glucose on the cytoplasmic side of ER and golgi membrane, potentially affecting tumor drug resistance." (PMID 36568076, 2022). "GCS expression was higher in CCA tumor tissues than that of GBA1, GBA2, and GBA3." (PMID 35330102, 2022). "Additionally, the expression level of GCS was higher in the CCA tumor tissues than the other glucocerebrosidase (GBA1, GBA2, and GBA3)." (PMID 35330102, 2022).
cancer (5 papers, 2014 to 2025). A tumor composed of atypical neoplastic, often pleomorphic cells that invade other tissues. "These include the “Sphingolipid signaling pathway”, in which GBA2 participates, “Axon guidance” that is associated with neuronal function, as well as the “Insulin resistance” and “Proteoglycans in cancer”." (PMID 35277195, 2022). "In a similar way, should the non-lysosomal GBA2 and sphingosine 1-phosphate be implicated, enzyme inhibitors of GBA2 and/or sphingosine kinases may be attractive strategies for the prevention of cancers in GD patients." (PMID 32085512, 2020). "Although the mechanism and function of extra-lysosomal GlcCer degradation are not well understood, GBA2 has recently been implicated in various pathologic conditions, such as neuronal diseases or cancer, which supports a role of GlcCer in cell growth, proliferation and immunity." (PMID 25141135, 2014). "Up-regulation of GCS is implicated in cancer progression and multi-drug resistance, but the role of glucosylceramide breakdown (including GBA1 and GBA2) in cancer is unclear." (PMID 35330102, 2022). "Thus, GBA2 is highly like to exert its functions on cancer cell growth via regulating ceramidelevel in the ceramide-S1P rheostat." (PMID 40636215, 2025). "However, the modulation mechanism by solanocapsine on either GBA2 or cancer cell growth is stillunknown." (PMID 40636215, 2025). "Increased expression of glucosylceramide synthase (GCS) contributes to drug resistance and the progression of various cancers; the expression profiles of GCS (UGCG) and the genes for glucocerebrosidases 1, 2, and 3 (GBA1, GBA2, and GBA3) were therefore studied in CCA." (PMID 35330102, 2022).
neurodegenerative disease (4 papers, 2015 to 2024). A disorder of the central nervous system characterized by gradual and progressive loss of neural tissue and neurologic function. "Because of the involvement of GBA2 in sphingolipid metabolism and the association of sphingolipid pathways with neurodegenerative diseases, we chose them as candidates for evaluation in relation to SA pathogenesis through targeted pathway analysis." (PMID 32937819, 2020). "Sphingolipid relevant pathways are directly correlated with GBA2-associated SA, due to the catalytic role of GBA2 in the sphingolipid metabolism, while apoptosis and calcium signaling have been associated with several neurodegenerative diseases based on bibliography." (PMID 35277195, 2022).
neurological disorders (3 papers, 2015 to 2020). "Thus far, limited insights into the physiological role of GBA2 have been obtained by pharmacologically inhibiting the enzyme, by gene ablation, and through the identification of mutations in the GBA2 gene in humans affected with neurological diseases." (PMID 32492073, 2020).
infection (2 papers, 2014 to 2022). The state of being infected such as from the introduction of a foreign agent such as serum, vaccine, antigenic substance or organism. "Our qRT-PCR data revealed that sphingolipid metabolic key genes encoding enzymes: Cers2, Gba2, Gla, Asah1, Asah2, Acer2, Acer3, Neu3, Sgpp1, and Sphk1 were robustly upregulated in mRNA levels by the infection of C. sinensis." (PMID 36339341, 2022). "In addition, the residual GBA1 and GBA2 activities associated with heat killed bacteria were measured by enzymatic assays on the amounts of heat killed PAO1 from 20 to 30-fold higher compared to those used for the cell infection." (PMID 25141135, 2014). "In CF bronchial cells, inhibition of GBA2 by miglustat or Genz-529648 significantly reduced the induction of IL-8 mRNA levels and protein release following infection by P. aeruginosa." (PMID 25141135, 2014). "A significant increase in total β-glucosidase, GBA1 and GBA2 activities were observed in response to infection." (PMID 25141135, 2014). "This study aimed to probe the molecular basis for the anti-inflammatory activity of miglustat by examining specifically the role of GBA2 following the infection of CF bronchial epithelial cells by P. aeruginosa." (PMID 25141135, 2014). "Miglustat, a well-characterized iminosugar-based inhibitor of β-glucosidase 2 (GBA2), has shown promise in CF treatment because it reduces the inflammatory response to infection by P. aeruginosa and restores F508del-CFTR chloride channel activity." (PMID 25141135, 2014).
inherited diseases (1 paper, 2020). "The enzyme β-glucosidase 2 (GBA2) is clinically relevant because it is targeted by the drug miglustat (Zavesca®) and because it is involved in inherited diseases." (PMID 32492073, 2020).
GBA2 also shares sentences with these, for which no sentence is quoted: cerebellar ataxia (6 papers); Spastic paraplegia (4); cataract (2); Cerebellar atrophy (2); epilepsy (2); Infertility (2); Marinesco-Sjögren syndrome (2); Obesity (2); Parkinsonism (2); brain malformations (1); breast carcinoma (1); cholangiocarcinoma (1); developmental delay (1); Gait ataxia (1); hypogonadism (1); Insulin resistance (1); mental disorder (1); paraplegia (1); skin cutaneous melanoma (1); Spasticity (1); Tremor (1); Troyer syndrome (1).